APOE (apolipoprotein E)
Diseases named in the same sentence as APOE in open-access papers (continued):
Sharing a sentence is not in itself a finding about the gene and the disease.
dementia (continued). "Those who developed dementia more often had APOE ε4 allele and mild cognitive impairment at enrollment." (PMID 33948250, 2020). "APOE ɛ4 carriers have been reported to be more susceptible to environmental risk factors for dementia, including smoking, heavy alcohol consumption, physical inactivity, and high intake of saturated fats." (PMID 32081835, 2020). "While the associations of midlife LIBRA scores with dementia or MCI risk were not influenced by the APOE ε4 allele in the present study, a significant interaction with APOE ε4 carrier status was found for late‐life LIBRA index in relation to dementia risk." (PMID 31736136, 2020). "There is emerging evidence for plasma APOE as a risk factor for dementia, and to a lesser extent for ischemic heart disease, but the associations seem to be independent of APOE genotype." (PMID 32646381, 2020). "In this study, apolipoprotein E ε4 genotype was associated with the development of incident dementia, and higher blood pressure was associated with increased risk of incident stroke in CADASIL patients with predominant p.Arg544Cys mutation." (PMID 33328970, 2020). "ApoE e4e4 associations with test positivity and mortality were little affected by excluding dementia and other ApoE e4-associated diagnoses reported before March 2017: future work should include recent preexisting diagnoses." (PMID 32623451, 2020). "APOE ε4, diabetes, heart disease, stroke, and delirium independently increased the risk of late-life dementia, controlling for the competing risk of death." (PMID 32767997, 2020). "It is worth noting that the association between a low APOE level and the higher risk of dementia has been recently supported by a Mendelian randomization study performed on two large population cohorts (106,562 and 75,260 individuals)." (PMID 33066592, 2020). "Firstly, our results provide further evidence of a positive and independent association between obesity and dementia risk, after controlling for potential confounders, including APOE-ε4 carrier status." (PMID 32575116, 2020). "A recent study focuses on the relationship at the gene–gene and gene–environment levels of the interactions between CHRNA7 polymorphism, apolipoprotein E (APOE) ε4 carriers, and smoking on risk of dementia." (PMID 32532978, 2020). "Higher late‐life LIBRA scores were related to higher risk of MCI up to 10 years later and to higher dementia risk, although the latter was restricted to APOE ε4 non‐carriers." (PMID 31736136, 2020). "APOE was significantly associated with dementia severity with each ε4 allele associated with an increase in 0.492 (P = 2.14 × 10−9) in pre-mortem CDR score." (PMID 33376986, 2020). "The presence of APOE‐ε4 was associated with an earlier dementia diagnosis by approximately 24.9 months (β = −.29; 95% CI = −.38 to −.20; P < .001)." (PMID 32187654, 2020). "For the association between ApoE gene polymorphism ε2/ε3/ε4 and dementia, there were 27 studies with 3136 dementia patients and 3103 healthy controls." (PMID 32398686, 2020). "Specifically, the presence of apoC3 in HDL appeared to modulate the association of apoE in HDL with risk of dementia and AD." (PMID 32648923, 2020). "Recent evidence suggests that a high glycemic load (GL) diet is a risk factor for dementia, especially among apolipoprotein E ε4 allele (APOE4) carriers, while its association with cognitive decline is poorly known." (PMID 33255701, 2020). "Meanwhile, APOE ε4 allele is closely associated with elevated levels of plasma lipids and has been demonstrated to increase the risk of dementia and cognitive impairment." (PMID 32581766, 2020). "Considering the sample size of younger-old individuals in our study, more studies are warranted to confirm the link of job demand-control status to dementia and the modifying effect of APOE ɛ4 allele." (PMID 32081835, 2020). "In relation to other types of dementia, the APOE-ε4 allele is associated with increased risk of dementia with Lewy bodies (DLB)." (PMID 32054532, 2020).
dementia (continued). "Respondents advised highlighting MCI subtypes and specifying subgroups such as individuals with known ApoE genetic status (associated with AD risk), various dementia subtypes and dementia presentations complicated by depression or comorbid conditions." (PMID 31884708, 2020). "Theyconcluded that APOE (4 allele carriage is associated withan increased prevalence and incidence of dementia in populationscharacterized by African/European admixture." (PMID 32973976, 2020). "Plasma concentrations of apoE themselves are associated with lower risk of dementia and AD, even after accounting for the APOE genotype." (PMID 32648923, 2020). "This provides further evidence that the APOE ε4 allele influences late-life dementia risk through its association with β-amyloid deposition, while vascular risk influences late-life brain health through nonamyloidogenic pathways." (PMID 31682678, 2020). "Here, we used a large cohort to investigate how the APOE promoter polymorphism influenced brain functional activation and connectivity areas in non-dementia elderly." (PMID 32694990, 2020). "Although we, and now several others, have reported increased cross-sectional risk for dementia in people with PD who inherited an APOE ε4 allele, our results here showed only a trend to an increased rate of progression to dementia in this group." (PMID 32885039, 2020). "Among all the risk factors considered, APOE ε4, diabetes, heart disease, stroke and delirium independently increased dementia incidence in late life." (PMID 32767997, 2020). "For people with DS and dementia, carrying at least 1 APOE ε4 allele was associated with increased mortality risk 7-fold." (PMID 30452522, 2019). "This suggests that a vast part of excess risk for APOE-ε4 is via its effect on dementia pathology, but that other mechanisms also play a role in carriers of the APOE-ε2 and to a lesser extent APOE-ε4 allele." (PMID 31356640, 2019). "As expected, another well-known protective factor, the presence of APOE ε2ε3 allele, appeared to be also shielding against the effect of age on the probability of dementia." (PMID 31022959, 2019). "Meanwhile, Tau in cerebrospinal fluid (CSF) and Apolipoprotein E ε4 (APOE 4) are all associated with increased risk of progression from MCI to dementia and they are the robust predictors of AD." (PMID 31440157, 2019). "Previous studies have shown that decreased serum ApoE levels and hypomethylation in the CpG-252 (cg18799241) are risk factors for the development of dementia." (PMID 30897703, 2019). "Noteworthy, high ApoE protein in CSF of AD patients has been found to be associated with dementia and in vivo pathological signs of AD." (PMID 31417354, 2019). "This association makes sense assuming that APOE ε4 alleles were inherited from an affected parent and therefore represented a shared dementia risk factor." (PMID 31617930, 2019). "Having lower RAVLT immediate and delayed recall test scores (HR 0.94, 95% CI 0.91–0.96 and HR 0.81, 95% CI 0.75–0.88, respectively) and being APOE ε4 carrier (HR 2.03, 95% CI 1.18–3.46) were associated with a higher risk of dementia." (PMID 31805990, 2019). "Genetic factors, such as the apoE ε4 allele, and vascular risk factors, such as hypertension, can explain a proportion of dementia risk." (PMID 30830941, 2019). "Other explanations for gender disparity in the risk of dementia and AD are mainly due to lower educational attainment, a stronger Apolipoprotein E genotype effect, smaller head size, or slower cerebral brain volume in females." (PMID 31815145, 2019). "Although confirmatory studies in larger samples are required, we suggest that assessment of MCI should include plasma ApoE levels and APOE methylation levels in order to identify individuals at high risk of developing dementia." (PMID 30897703, 2019). "APOE ε4 genotype, early-onset epilepsy, multimorbidity, and living with family were all associated with earlier dementia diagnoses." (PMID 30452522, 2019).
dementia (continued). "APOE ε4 carriers and/or people with multiple comorbid health conditions were at increased risk of dementia and death, highlighting the need for good health care." (PMID 30452522, 2019). "For those with dementia, APOE ε4 carriers had a 7-fold increased risk of death (hazard ratio [HR], 6.91; 95% CI, 1.756-27.195)." (PMID 30452522, 2019). "Intriguingly, even the e4 allele of apolipoprotein E (ApoE4), the most common risk factor for AD-related senile dementia, has been shown to upregulate the activity of MERCs." (PMID 31497601, 2019). "In recent years, genes associated with dementia and AD, such as APOE, have received increased research attention." (PMID 31722673, 2019). "After accounting for dementia in our study, associations with mortality attenuated for APOE-ε4, but were virtually unaltered for APOE-ε2." (PMID 31356640, 2019). "APOE ε4 genotype has previously been linked to an increased risk of conversion from MCI to dementia, but studies have primarily focused on heterogeneous MCI populations, without stratifying by amyloid pathology." (PMID 31805990, 2019). "In those hetero- and homozygous for the ApoE-ε4 allele, dementia risk was increased in persons with medium and high levels of IGF-I receptor stimulating activity at baseline, compared to those with low IGF-I receptor stimulating activity at baseline." (PMID 30809143, 2019). "The relationship between obesity and genetic risk of dementia, notably APOE genotype, remains not fully understood." (PMID 30735826, 2019). "APOE ε4 and systolic blood pressure were associated with the risk of recurrent haemorrhage, ischaemic stroke and post-haemorrhage dementia, depression and gait impairment (all P < 0.05)." (PMID 32954261, 2019). "APOE ε4 and systolic blood pressure interacted to increase the risk of recurrent haemorrhage, ischaemic stroke, dementia and gait impairment (all interaction P < 0.05)." (PMID 32954261, 2019). "We found ~ 2-fold higher levels in LDB (4.55; 2.57–12.27 ng/g; n = 14) than PD (2.59; 1.16–4.16 ng/g; n = 12), indicating that factors besides APOE ε4 status influence the association between Δtau314 and dementia in Lewy body disease." (PMID 31362787, 2019). "Of note, apolipoprotein E plays a fundamental role in cholesterol metabolism and has been extensively linked to cardiovascular disease and dementia, with the APOE ε4 allele proposed to be a major risk factor for developing AD." (PMID 30691140, 2019). "Sex (women diagnosed earlier), APOE genotype, multimorbidity, early-onset epilepsy, and living situation were found to be independently associated with age at dementia diagnosis." (PMID 30452522, 2019). "Due to the independent and non-interacting nature of the APOE and PBV associations, the prevalence of dementia in APOE ε3ε4/ε4ε4 persons with high PBV values (>1 SD from mean) was observed to be the same as APOE ε3ε3 persons (14.3% versus 14.0%)." (PMID 31022959, 2019). "In this review, we focus on the influence of genetic factors, including the APOE gene, the interaction between APOE and other genes, and the polygenic risk factors for cognitive function and dementia." (PMID 30866553, 2019). "The APOE ε4 allele is considered a significant risk factor for dementia and several studies examined the effect of APOE alleles on plasma Aβ levels, with inconsistent and variable results." (PMID 31389176, 2019). "Previous APOE-related studies also investigated the effects of associations between APOE and other gene polymorphisms on cognition and dementia." (PMID 30866553, 2019). "In this subset, we identified consistent interaction between SBP and APOE ɛ4 in determining the risk of dementia and gait impairment." (PMID 32954261, 2019). "Different socio-economic factors including age and education, along with APOE genotype, and dementia risk modulate these episodic memory trajectories." (PMID 30462667, 2018).
dementia (continued). "The small number of PD cases with dementia in each study, the significant heterogeneity of odds ratios between studies, and evidence of publication bias limits the confidence of the APOE and dementia in PD association." (PMID 29692703, 2018). "The results of both logistic regression analyses demonstrated that APOE ɛ4 remains an important risk factor for dementia after age 79 years (logistic regression model 2: Odds Ratio (OR) 2.52 (95% confidence interval: 1.50, 4.22), p < 0.001)." (PMID 30180830, 2018). "A second cumulative incidence plot confirmed that the presence of an APOE ɛ4 allele was associated with an increased risk for dementia." (PMID 30180830, 2018). "Recently, the increased risk for dementia in T2DM patients was also shown to be associated with ApoE genotypes." (PMID 29896424, 2018). "The individual and combined effects of cytokine levels on dementia were evaluated after adjusting for potential covariates (lifestyle factors, demographics, disability, cognitive function, and presence of the APOE e4 allele) and a Bonferroni correction." (PMID 30510525, 2018). "Possession of an APOE ε4 allele has been shown to increase the risk of dementia, and Alzheimer’s dementia in particular." (PMID 29745686, 2018). "This confirms previous suggestive findings in a cohort of Italian centenarians who were free of dementia or any other major age-related conditions, which had a similar enrichment of the APOE-ε2 allele." (PMID 30362018, 2018). "Apolipoprotein E (ApoE) gene polymorphism has been implicated in predisposition to diabetes and dementia in old population, but the results from the different studies were inconclusive." (PMID 29896424, 2018). "The presence of an APOE ɛ4 allele was however an important predictor for dementia (HR 2.85, p < 0.001, n = 416)." (PMID 30180830, 2018). "In this subsample, low insulin predicted dementia (HR 3.01, 95% CI 1.56–5.84) compared to the medium insulin tertile independently of higher APOE ε4 allele frequency (HR 2.18, 95% CI 1.29–3.67) per allele (data available from Dryad, right column)." (PMID 29997193, 2018). "As was observed in a previous study of the LBC1921, the presence of an APOE ɛ4 allele was however associated with an increased risk for dementia." (PMID 30180830, 2018). "While the potency of APOE ε4 as a risk factor has been shown to reduce in oldest-age, the same meta-analysis confirms that it continues to increase the risk for dementia in oldest-age cohorts." (PMID 29745686, 2018). "One quarter of the population carries the ε4 variant of the APOE gene, which is one of the strongest risk factors for dementia." (PMID 29414991, 2018). "The epsilon 4 allele of apolipoprotein E (ApoE) remains the strongest genetic risk factor for dementia; it is the lowest affinity ApoE isoform for cholesterol uptake by the lipoprotein receptor." (PMID 29501047, 2018). "ApoE gene polymorphisms have also been implicated in predisposition to diabetes and dementia, but the results from the different studies were inconclusive." (PMID 29896424, 2018). "For example, lower plasma level apoE has been reported to be associated with lower cognitive function and higher risk of dementia." (PMID 29739406, 2018). "The APOE ε4 carrier status by dementia status interaction was associated with Raven’s Matrices test score at age 79 (p = .006), but not Logical Memory or Verbal Fluency test scores." (PMID 29745686, 2018). "Our finding that the APOE ε4 genotype increases the risk for cognitive decline regardless of age is at odds with some earlier studies that reported a decrease of risk for dementia with age but is consistent with others." (PMID 30126373, 2018). "The presence of at least one APOE ε4 allele has also been shown to increase the risk for dementia after age 79 in LBC1921 (Sibbett, Russ, Deary, & Starr, 2017b)." (PMID 29745686, 2018).
dementia (continued). "Among APOE ε4 carriers, individuals exposed to ≥ 20 years of shift work and night work had increased dementia risk compared to day workers." (PMID 30076495, 2018). "Compared to those with Stable trajectory, individuals characterized as Decliners were more likely to have non-white ethnic background, fewer years of education, a higher frequency of ε4 allele at APOE gene and five times more likely to develop dementia." (PMID 30462667, 2018). "The presence of the APOE‐ε4 allele increases deposition of beta‐amyloid plaques, and has been shown to independently contribute to the prediction of conversion dementia when measured by tests of episodic memory such as the CVLT‐II." (PMID 28948085, 2017). "Many epidemiological studies suggest that the APOE ε4 allele carrier status of individuals have associations between modifiable lifestyle risk factors, and dementia and AD." (PMID 28230730, 2017). "These adverse PM2.5 effects varied by APOE allele, with ɛ3/3<ɛ3/4<ɛ4/4 for both global cognitive decline (ɛ3/3: HR=1.65; ɛ3/4: HR=1.93; ɛ4/4: HR=3.95) and all-cause dementia (ɛ3/3: HR=1.68; ɛ3/4: HR=1.91; ɛ4/4: HR=2.95)." (PMID 28140404, 2017). "Subgroup analyses showed that the cutpoint for the dementia group and for APOE ε4 allele carriers was also higher in the 2008–2015 group than in the 2001–2007 group." (PMID 28193256, 2017). "We found that the development of dementia was influenced by the APOE ε4 allele (HR = 1.90; P = 0.03) and GBA deleterious variants (HR = 2.59; P = 0.01)." (PMID 28399184, 2017). "Similar to Western societies, age, sex, family history of dementia, and apolipoprotein E epsilon 4 allele are proven to be the major risk factors for dementia in Taiwan." (PMID 28403222, 2017). "To this end, we collected [123I]FP-CIT SPECT images and long-term clinical data on the developement of dementia, and genotyped APOE, MAPT, COMT and SNCA risk polymorphisms, as well as GBA screening in a cohort of 298 PD patients from our centre." (PMID 28399184, 2017). "We also used subdistribution hazard regression to model relative hazard based on age, APOE genotype, sex, education, family history of dementia, vascular risk, subjective memory concerns, and baseline cognitive performance." (PMID 28323826, 2017). "In both models the presence of an APOE ɛ4 allele increased the risk of dementia (model 2 OR: 2.37, 95% CI: 1.37, 4.07)." (PMID 28578665, 2017). "In summary, the results of this study suggest that the presence of an APOE ɛ4 allele is a risk factor for incident dementia from age 79–95." (PMID 28578665, 2017). "We included SNPs in APOE and adjusted the tests for the APOE-ε4 allele, a known risk factor for dementia." (PMID 28983317, 2017). "Specifically, the apolipoprotein E gene (APOE) ε4 allele has been associated with an increased risk of dementia and deficits in memory and verbal fluency." (PMID 28399184, 2017). "A number of studies have suggested a decline in the importance of APOE ɛ4 as a risk factor for dementia with advancing age." (PMID 28578665, 2017). "Our estimates of lifetime risk for dementia for APOE-e4/e4 individuals from the Framingham Heart Study and the Rotterdam Study are in the 31%–40% range." (PMID 28323826, 2017). "The results of this study reinforce the importance of the APOE ɛ4 allele as a risk factor for the development of dementia." (PMID 28578665, 2017). "Depression in late life has also been linked to dementia, particularly in those carrying the ε4 variant of the APOE gene that predisposes to AD in depressed individuals." (PMID 28230730, 2017). "All patients with dementia (AD, MD and VaD) were less educated, had worse cognitive performance and showed a higher frequency of the APOE ε4 allele when compared to the control group." (PMID 28421328, 2017). "In an analysis of four longitudinal cohort studies, Deborah Blacker and colleagues estimate the risk of mild cognitive impairment and dementia by APOE-status." (PMID 28323826, 2017).